SAT1 (spermidine/spermine N1-acetyltransferase 1)
Diseases named in the same sentence as SAT1 in open-access papers (continued):
Sharing a sentence is not in itself a finding about the gene and the disease.
brain tumors (3 papers, 2021 to 2022). "Additionally, Sat1 is found to ameliorate resistance to ionizing radiation and upregulated in brain tumors." (PMID 34836197, 2021).
calcium oxalate urolithiasis (3 papers, 2013 to 2017). Urolithiasis in which the composition of the stones is predominantly calcium oxalate. "Loss of Sat1 leads to hyperoxaluria, hyperoxalemia and calcium oxalate urolithiasis." (PMID 29183349, 2017). "While the mechanism for nephrocalcinosis, calcium oxalate urolithiasis, and increased serum calcium is not totally clear, these phenotypes associate with decreased Sat1 function, suggesting they may be specific to anion transport rather than sulfate transport." (PMID 27412988, 2016). "To investigate the possible involvement of SAT1 in human urolithiasis, we screened the SLC26A1 gene in a cohort of 13 individuals with recurrent calcium oxalate urolithiasis, which is the commonest type." (PMID 24250268, 2013).
co-infection (3 papers, 2020 to 2022). "This study is possible thanks to a co-infection of two SAT1 viruses, creating two co-occurrent subpopulations with a small sequence divergence of about 3% inside the buffalo hosts." (PMID 31905219, 2020). "However, the first-passage sequences from #6/SAT1, #61/SAT1, and #36/SAT1 may have been incorrectly called due to co-infection based on their divergence from the plaque-isolated sequences." (PMID 35632639, 2022).
Hyperoxaluria (3 papers, 2013 to 2017). Increased excretion of oxalates in the urine. "Loss of SAT1 in mice led to disturbances in sulfate homeostasis (hyposulfataemia and hypersulfaturia), as well as hyperoxalaemia and hyperoxaluria." (PMID 24250268, 2013). "SLC26A1 encodes the sulfate anion transporter 1 (SAT1) protein, and its loss in mice leads to hyperoxaluria and calcium oxalate renal stones." (PMID 24250268, 2013). "The finding of calcium oxalate stones in SAT1 null mice in this landmark paper was remarkable because rodents are extremely refractive to forming stones, even when mild-moderate hyperoxaluria occurs." (PMID 24250268, 2013). "However, in EG-treated males, a high production of oxalate in the liver, and unchanged but high abundance of sat-1 protein in hepatocytes and renal proximal tubules may contribute to hyperoxalemia and hyperoxaluria." (PMID 26526882, 2015). "On the other hand, in the presence of elevated expression of hepatic and renal sat-1 in EG-treated females, a relatively weak oxalemia and absence of hyperoxaluria suggest a possible protective role of the sat-1 protein up-regulation." (PMID 26526882, 2015). "Knockout of sat-1 and CFEX induced oxalemia, hyperoxaluria, and oxalate nephrolithiasis." (PMID 26526882, 2015). "Mice lacking sat-1 or CFEX develop hyperoxalemia, hyperoxaluria, calcium-oxalate nephrocalcinosis, and tubular damage." (PMID 26526882, 2015).
lung adenocarcinoma (3 papers, 2023 to 2024). A carcinoma that arises from the lung and is characterized by the presence of malignant glandular epithelial cells. "The transcription factor MNT binds to the SAT1 promoter region and represses its transcription, leading to ferroptosis and chemotherapy resistance in lung adenocarcinoma." (PMID 38831092, 2024). "ASMTL-AS1 impedes the malignant progression of lung adenocarcinoma by regulating SAT1 to promote ferroptosis." (PMID 37202394, 2023). "Here, our study demonstrates that MAX’s Next Tango (MNT), by involving itself in the spermidine/spermine N1-acetyltransferase 1 (SAT1)-related ferroptosis pathway, promotes the proliferation of lung adenocarcinoma (LUAD) cells and diminishes their sensitivity to chemotherapy." (PMID 38831092, 2024).
Parkinson disease (3 papers, 2017 to 2025). A progressive degenerative disorder of the central nervous system characterized by loss of dopamine producing neurons in the substantia nigra and the presence of Lewy bodies in the substantia nigra and locus coeruleus. "Having first identified a clinically relevant mutation in a potential PRE within the 3’UTR of SAT1, we wished to determine if other Parkinson’s Disease-associated genes contained PRE sites in their 3’UTRs." (PMID 36174040, 2022). "A small collection of genes has been linked to Parkinson’s disease including LRRK2, SAT1, and SNCA, the latter of which encodes the protein alpha-synuclein that aggregates in Lewy bodies as a hallmark of the disease." (PMID 36174040, 2022). "Similarly in Parkinson's patients, changes in polyamine levels also have been found, the decreased expression of polyamine metabolic enzyme SAT1 led to an increase in polyamine levels, which in turn reduced the cognitive performance of patients with Parkinson 's disease through the NMDAr pathway." (PMID 40234982, 2025).
Anxiety (2 papers, 2010 to 2023). Intense feelings of nervousness, tension, or panic often arise in response to interpersonal stresses. "Studies have identified associations between genetic variants in spermidine/spermine N1-acetyltransferase (SAT1) and both anxiety and suicide, and several polymorphisms appear to play important roles in determining gene expression." (PMID 21152090, 2010). "Overall, each gene was associated with at least one main outcome: anxiety (SAT1, SMS), mood disorders (SAT1, SMOX), and suicide attempts (SAT1, OATL1)." (PMID 21152090, 2010). "However, a 22-year longitudinal study of 1255 Canadian individuals showed that the N1-acetyltransferase (SAT1) and SAT1, spermine synthase (SMS) polymorphisms are associated with anxiety and suicide attempts." (PMID 38069051, 2023).
anxiety disorder (2 papers, 2010 to 2022). A category of psychiatric disorders which are characterized by anxious feelings or fear often accompanied by physical symptoms associated with anxiety. "In this study, SMS, which is involved in spermine biosynthesis, demonstrated strong associations with anxiety disorders through both main genetic effects as well as through a gene-gene interaction with SAT1." (PMID 21152090, 2010). "Disruptiveness did not demonstrate mediating effects with respect to mood disorders or anxiety disorders, although it was significantly linked to rs3764885 (SAT1) (r = −0.09, P = 0.0009) which predicted anxiety disorders and mood disorders." (PMID 21152090, 2010). "In addition to the main genetic effects, we identified a gene-gene interaction between SMS and SAT1 in conferring risk for anxiety disorders." (PMID 21152090, 2010). "Individuals with homo/heterozyosity for the G alleles in rs3764885 (SAT1) and in rs6654100 (SMS) had an elevated risk for anxiety disorders." (PMID 21152090, 2010). "As there was a high correlation between two of the pairs of SNPs that were significantly associated with anxiety disorders (rs10521911 and rs6654100 in SMS: r2 = 0.96; and rs6526342 and rs3764885 in SAT1: r2 = 0.86), we randomly dropped one of the SNPs of each pair from the interaction analyses." (PMID 21152090, 2010). "Several SAT1 polymorphisms displayed disease-specific risk alleles, and polymorphisms in this gene were involved in gene-gene interactions with SMS to confer risk for anxiety disorders, as well as gene-environment interactions between childhood physical abuse and mood disorders." (PMID 21152090, 2010). "Two SAT1 and five SMS SNPs exhibited recessive modes of inheritance regarding the prediction of anxiety disorders, while three SMS SNPs were significant in the dominant model." (PMID 21152090, 2010).
Ataxia (2 papers, 2020 to 2022). Ataxia refers to impaired coordination of voluntary muscle movement. "The Smox/Sat1-dKO mice died or were euthanized between 16 and 20 weeks of age due to either severe ataxia or a weight loss of greater than 20%, as required by our protocol." (PMID 33054763, 2020). "Specifically, the number of microglia that expressed IBA1 was increased, as was the expression of GFAP in the cerebellum of Smox/Sat1-dKO mice as early as 8 weeks of age, and this correlated with the severity of ataxia." (PMID 33054763, 2020). "The α-Synuclein levels were also elevated in the cerebrum of Smox/Sat1-dKO at 8 (mild ataxia) and 14+ (severe ataxia) weeks of age, but their expression levels were lower in comparison to those found in the cerebellum of the same animals." (PMID 33054763, 2020). "This revealed that Smox/Sat1-dKO mice developed mild ataxia as early as 8 weeks of age that progressively advanced with age." (PMID 33054763, 2020). "Although Smox/Sat1-dKO mice are viable and normal at birth, they all develop progressive ataxia and exhibit severe deficits in movement as early as 12 weeks of age (8-week-old mouse and video 2, 14+-week-old mouse)." (PMID 33054763, 2020). "Our findings support a model where the elevated levels of spermine and increased polyamination of target proteins such as α-Synuclein by TGM2 in Smox/Sat1-dKO Purkinje cells drive the development and progression of ataxia." (PMID 33054763, 2020). "Treatment of Smox/Sat-1 double knock-out mice (Smox/Sat1-dKO) with transglutaminase inhibitors decreased the expression and aggregation of polyamines, reduced the severity of cerebellar damage, and significantly delayed the onset of ataxia." (PMID 35893120, 2022). "Finally, the development of severe ataxia in Smox/Sat1-dKO mice was accompanied by accumulation of CD3+, CD4+, and CD8+ lymphocytes in the leptomeninges." (PMID 33054763, 2020). "Smox/Sat1-dKO mice are normal at birth, but develop progressive cerebellar damage and ataxia." (PMID 33054763, 2020). "Based on our results, we propose that prolonged deficits in polyamine catabolism, increased TGM2 activity, and enhanced α-Synuclein expression, polyamination, and aggregation result in the activation of a circuit that leads to cerebellar injury and ataxia in Smox/Sat1-dKO mice." (PMID 33054763, 2020). "Finally, there were clear roles of transglutaminase-2 (TGM2) in the cerebellar pathologies manifest in Smox/Sat1-dKO mice, as pharmacological inhibition of transglutaminases reduced the severity of ataxia and cerebellar injury in Smox/Sat1-dKO mice." (PMID 33054763, 2020). "Indeed, there are no apparent injuries to any other organs or tissues in Smox/Sat1-dKO mice, despite the fact that these mice manifest profound, fully penetrant ataxia." (PMID 33054763, 2020).
endometrial cancer (2 papers, 2017 to 2025). Primary or metastatic malignant neoplasm involving the endometrium (mucous membrane that lines the endometrial cavity). "Reduced levels of SAT1 in endometrial cancers would suggest this may reflect a loss of ovarian steroid anti-proliferative controls which is the hallmark feature of endometrial cancer." (PMID 29240775, 2017). "Future studies should explore the role of SAT1, SMS and SRM in the polyamine addiction of endometrial cancer, in particular the mechanisms that cause some of these to be more DFMO sensitive than others." (PMID 29240775, 2017).
female infertility (2 papers, 2010 to 2017). Diminished or absent ability of a female to achieve conception. "Overexpression of SAT1 in mice leads to permanent hair loss at the age of 3 to 4 weeks and female infertility due to ovarian hypofunction and hypoplastic uteri." (PMID 28414775, 2017). "A transgenic increase of SAT1 expression in mice showed a variety of defects such as hair loss, female infertility, impaired lipid metabolism and predisposition to develop pancreatitis." (PMID 19782748, 2010).
hypersulfaturia (2 papers, 2017 to 2023). "A role of the anion transporter SLC26A1 (Sat1) for sulfate reabsorption in the kidney is supported by the observation of hyposulfatemia and hypersulfaturia in Slc26a1-knockout mice." (PMID 36719378, 2023). "In the murine model, targeted disruption of renal sulfate transporter genes NaS1 and Sat1 leads to hyposulfatemia and hypersulfaturia." (PMID 29183349, 2017).
ischemic cardiomyopathy (2 papers, 2021 to 2022). Ischemic cardiomyopathy is a cardiomyopathy in which a weakness in the muscle of the heart due to inadequate oxygen delivery to the myocardium with coronary artery disease being the most common cause. "Overexpression of polyamine metabolic enzymes such as ODC and SAT1 has been linked to ischemic cardiomyopathy, and polyamines like N8AS serve as a potential biomarker for ischemic cardiomyopathy." (PMID 34902085, 2021).
kidney damage (2 papers, 2014 to 2024). "To examine the role of polyamine catabolism in the mediation of renal injury caused by RLDC, we compared the severity of kidney damage, polyamine levels, the onset of renal fibrosis, and kidney function in WT compared to Sat1-KO and Smox-KO mice." (PMID 38540254, 2024).
lupus (2 papers, 2015 to 2025). "Generation of mouse models carrying the orthologous variants has identified novel genes causing monogenic or oligogenic SLE such as TLR7, UNC93B1, SAT1 and TNIP13–6, expanding the list of monogenic lupus causes." (PMID 40386946, 2025).
myocardial infarction (2 papers, 2022 to 2024). Gross necrosis of the myocardium, as a result of interruption of the blood supply to the area, as in coronary thrombosis. "Sat1 inhibition significantly increased EF, ameliorated cardiac damage and reduced myocardial infarction size." (PMID 39605920, 2024). "The expression of ACSL4, LAMP2, PTEN, PTGS2, and SAT1 were different in the early and late stages of myocardial infarction." (PMID 36407421, 2022).
nephrocalcinosis (2 papers, 2013 to 2016). Nephrocalcinosis is a disorder that occurs when too much calcium is deposited in the kidneys. "Of great interest is the finding of a nonconservative amino acid substitution (M132T) within a predicted transmembrane domain of SAT1, in one patient with severe nephrocalcinosis." (PMID 24250268, 2013).
Obesity (2 papers, 2024). Accumulation of substantial excess body fat. "In a mouse model of diet-induced obesity, chemically activating Sat1 via the synthetic agent triethylenetetramine dihydrochloride stimulated autophagy, reduced weight, and improved both fatty liver and glucose intolerance." (PMID 39411517, 2024). "β3AR signaling was reported to activates the spermidine/spermine N1-acetyltransferase (SAT1) in adipocytes to promote WAT browning and prevent high-fat diet (HFD)-induced obesity." (PMID 39267778, 2024).
osteosarcoma (2 papers, 2022 to 2023). A usually aggressive malignant bone-forming mesenchymal neoplasm, predominantly affecting adolescents and young adults.
ovarian hypofunction (2 papers, 2015 to 2017). "Female mice overexpressing Sat1 mRNA, whose product is a rate-limiting enzyme in polyamine catabolism, were found to be infertile due to ovarian hypofunction and hypoplastic uteri." (PMID 26445099, 2015).
renal fibrosis (2 papers, 2024). A final common manifestation of a wide variety of chronic kidney diseases characterized by glomerulosclerosis and tubulointerstitial fibrosis. "The adverse role of enhanced polyamine catabolism in the mediation of kidney injury in RLDC is further supported by the reduction in renal injury, better preservation of renal function, and reduced renal fibrosis in Sat1-KO and Smox-KO compared to WT mice." (PMID 38540254, 2024). "Comparing the severity of renal fibrosis using Masson Trichrome staining, it was demonstrated that Sat1-KO and Smox-KO mice had significantly reduced levels of fibrosis compared to their WT counterparts." (PMID 38540254, 2024). "In contrast, the protein expression of SAT1, an enzyme that positively regulates spermine catabolism, also appeared to slightly increased but lacked correlation with renal fibrosis and eGFR." (PMID 38775007, 2024).
Sepsis (2 papers, 2014 to 2023). Sepsis is defined as life-threatening organ dysfunction caused by a dysregulated host response to infection. "The ferroptosis-related genes (NOX4, HMOX1, POR, SAT1, etc.)were highly expressed in sepsis-induced cardiomyopathy model." (PMID 37035738, 2023).
urolithiasis (2 papers, 2013 to 2015). Stone(s) within the urinary tract. "In rats, hepatic and renal sat-1 expression was higher in males than in females, which may contribute to a higher prevalence of urolithiasis in males." (PMID 26526882, 2015). "The role of sat-1 in development of sex-related urolithiasis has not been well investigated in in vivo animal models." (PMID 26526882, 2015).
acute kidney injury (1 paper, 2021). Sudden and sustained deterioration of the kidney function characterized by decreased glomerular filtration rate, increased serum creatinine or oliguria. "Transgene-enforced overexpression of SAT1 accelerates aging in mice as it enhances carcinogenesis, while its knockout protects against liver and kidney ischemia-reperfusion damage, CCL4-induced acute liver injury, and endotoxin- or cisplatin-induced acute kidney injury." (PMID 34517343, 2021).
alcohol use disorder (1 paper, 2025). "Also, a polymorphism in SAT1 has previously been associated with alcohol use disorder." (PMID 40401629, 2025).
asthma (1 paper, 2018). "However, the role of SAT1 in asthma needs to be explored further." (PMID 29316647, 2018). "Hence, induction of SAT1 and restoration of reduced levels of α9β1 integrin, both could be effective in relaxation of ASMCs contractions in asthma." (PMID 29316647, 2018).
autoimmune disease (1 paper, 2020). A disorder resulting from loss of function or tissue destruction of an organ or multiple organs, arising from humoral or cellular immune responses of the individual to their own tissue constituents. "Some other potential therapeutic targets for treating autoimmune diseases, such as SLE, are the polyamine synthesis (SMS, ODC, AMD1) and recycling (SAT1) enzymes, transglutaminases, peptidyl arginine deiminases (related to NETosis), and EBV genes." (PMID 34968240, 2020).
colorectal tumor (1 paper, 2022). "We note that four genes (SAT1, MT1E, HSP90AA1, and HNRNPH1) from a colorectal tumor tissue have interactions with HIV-1 proteins." (PMID 36290397, 2022).
Crohn disease (1 paper, 2025). A gastrointestinal disorder characterized by chronic inflammation involving all layers of the intestinal wall, noncaseating granulomas affecting the intestinal wall and regional lymph nodes, and transmural fibrosis. "By integrating multi-omics approaches, this study reveals a crucial connection between ferroptosis and immune microenvironment dysregulation in Crohn’s disease (CD), identifying seven hub ferroptosis-related differentially expressed genes (FEDGs): SCD, ATF4, SAT1, RPL8, MUC1, MTDH, and ATP6V1G2." (PMID 41515900, 2025).
dilated cardiomyopathy (1 paper, 2024). Cardiomyopathy which is characterized by dilation and contractile dysfunction of the left and right ventricles. "In our study, genes regulated by AP-1, namely CDKN1A, SAT1, and ZFP36, were found to be downregulated in DCM (dilated cardiomyopathy) myocardium compared to normal myocardium." (PMID 38886541, 2024).
enteroviral infections (1 paper, 2024). "Mechanically, trained tuft cells produced more IL-25, which suppressed enteroviral infections via SAT1-mediated intracellular polyamine deficiency." (PMID 39261649, 2024).
germ cell tumor (1 paper, 2025). A benign or malignant, gonadal or extragonadal neoplasm that originates from germ cells. "Together, these findings suggest that DPPA4 and PSMA7 promote tumor progression, whereas PAGE5 and SAT1 suppress progression in germ cell tumors." (PMID 41203637, 2025).
hyperuricemia (1 paper, 2025). An abnormally high level of uric acid. "The immunostaining results for SAT1 were consistent with the ELISA findings, suggesting that polyamine metabolism is also exacerbated in response to hyperuricemia." (PMID 40260285, 2025).